PSMD2 (proteasome 26S subunit ubiquitin receptor, non-ATPase 2)
Description:
Component of the 26S proteasome, a multiprotein complex involved in the ATP-dependent degradation of ubiquitinated proteins. This complex plays a key role in the maintenance of protein homeostasis by removing misfolded or damaged proteins, which could impair cellular functions, and by removing proteins whose functions are no longer required. Therefore, the proteasome participates in numerous cellular processes, including cell cycle progression, apoptosis, or DNA damage repair. Binds to the intracellular domain of tumor necrosis factor type 1 receptor. The binding domain of TRAP1 and TRAP2 resides outside the death domain of TNFR1.
Synonyms: TRAP2; S2; P97; MGC14274; Rpn1
Tractability: Small molecule: an approved drug acts on it; a structure with a bound ligand is known; a high-quality ligand is known. Antibody: its Gene Ontology location is reachable by antibodies, with high confidence. PROTAC: ubiquitination databases record sites on it; its protein half-life has been measured.
Target class: Enzyme
Gene: Protein-coding gene on chromosome 3 (184,299,157 to 184,309,054, forward strand). Ensembl gene ENSG00000175166.
Subcellular location (Human Protein Atlas): Centriolar satellite; Cytosol; Flagellar centriole; Cytokinetic bridge; Nucleoplasm
Pathways (Reactome):
Immune System: AMPK-induced ERAD and lysosome mediated degradation of PD-L1(CD274); Activation of NF-kappaB in B cells; Antigen processing: Ubiquitination & Proteasome degradation; CLEC7A (Dectin-1) signaling; Cross-presentation of soluble exogenous antigens (endosomes); Dectin-1 mediated noncanonical NF-kB signaling; Downstream TCR signaling; ER-Phagosome pathway; FCERI mediated NF-kB activation; GSK3B-mediated proteasomal degradation of PD-L1(CD274); Interleukin-1 signaling; NIK-->noncanonical NF-kB signaling; Neutrophil degranulation; SPOP-mediated proteasomal degradation of PD-L1(CD274); TNFR2 non-canonical NF-kB pathway
Cell Cycle: APC/C:Cdc20 mediated degradation of Securin; APC/C:Cdh1 mediated degradation of Cdc20 and other APC/C:Cdh1 targeted proteins in late mitosis/early G1; Autodegradation of Cdh1 by Cdh1:APC/C; Autodegradation of the E3 ubiquitin ligase COP1; Cdc20:Phospho-APC/C mediated degradation of Cyclin A; FBXL7 down-regulates AURKA during mitotic entry and in early mitosis; G2/M Checkpoints; SCF(Skp2)-mediated degradation of p27/p21; SCF-beta-TrCP mediated degradation of Emi1; Separation of Sister Chromatids; The role of GTSE1 in G2/M progression after G2 checkpoint; Ubiquitin-Mediated Degradation of Phosphorylated Cdc25A; Ubiquitin-dependent degradation of Cyclin D
Signal Transduction: Asymmetric localization of PCP proteins; Degradation of AXIN; Degradation of DVL; Degradation of GLI1 by the proteasome; Degradation of GLI2 by the proteasome; Degradation of beta-catenin by the destruction complex; GLI3 is processed to GLI3R by the proteasome; Hedgehog 'on' state; Hedgehog ligand biogenesis; MAPK6/MAPK4 signaling; Negative regulation of NOTCH4 signaling; Regulation of PTEN stability and activity
and 28 more pathways
Gene Ontology:
Molecular function: protein binding; enzyme regulator activity
Biological process: cellular response to type I interferon; proteasomal protein catabolic process; proteasome-mediated ubiquitin-dependent protein catabolic process; regulation of proteasomal protein catabolic process; response to oxidative stress; regulation of protein catabolic process
Cellular component: extracellular exosome; membrane; proteasome complex; cytosol; extracellular region; ficolin-1-rich granule lumen; nucleoplasm; proteasome accessory complex; proteasome regulatory particle; proteasome storage granule; secretory granule lumen; synaptic vesicle
Genetic constraint (gnomAD): Loss-of-function variants: 8 observed, 102.54 expected, observed/expected ratio (o/e) 0.078, 90% interval 0.045 to 0.14. The upper end of that interval is the gene's LOEUF score, 0.14, which puts it in group 1 of 6, group 1 being the genes least tolerant of losing a copy. Missense variants: 784 observed, 1,168.5 expected, observed/expected ratio (o/e) 0.67, 90% interval 0.63 to 0.71. Synonymous variants: 418 observed, 441.9 expected, observed/expected ratio (o/e) 0.95, 90% interval 0.87 to 1.03.
Homologues: Orthologues: chimpanzee PSMD2 (100% identical), macaque PSMD2 (99% identical), rabbit PSMD2 (99% identical), guinea pig PSMD2 (99% identical), pig PSMD2 (99% identical), mouse Psmd2 (99% identical), rat Psmd2 (99% identical), tropical clawed frog psmd2 (92% identical), dog PSMD2 (82% identical), Drosophila melanogaster Rpn1 (63% identical), Caenorhabditis elegans rpn-1 (54% identical), zebrafish PSMD2 (54% identical), and 1 more. Paralogues in human: PSMD1 (20% identical).
Diseases named in the same sentence as PSMD2 in open-access papers:
PSMD2 is named in the same sentence as 49 diseases in open-access papers, as found by Europe PMC text mining. Sharing a sentence is not in itself a finding about the gene and the disease. The quoted sentences say what the papers report.
breast carcinoma (24 papers, 2017 to 2025). "Studies have demonstrated that PSMD2 is significantly up-regulated in breast cancer and is associated with poor prognosis." (PMID 38523673, 2024). "In our study, the PARP3, POLR2K, PSMB1, and PSMD2 genes were significantly associated with the overall survival of patients with breast cancer, and the high expression levels of POLR2K, PSMB1, and PSMD2 were related to low survival rates." (PMID 37350936, 2023). "USP14 was reported to be associated with PSMD2 in breast cancer and it is considering as a major regulator of proteasome by ubiquitin chain disassembly." (PMID 31013812, 2019). "PSMD2 is significantly dysregulated in breast cancer and associated with poor prognosis." (PMID 34367229, 2021). "Moreover, three DDR genes, POLR2K, PSMB1, and PSMD2, which are closely linked to tumorigenesis, may be used as potential biomarkers for predicting the prognosis of patients with breast cancer." (PMID 37350936, 2023). "Knockdown of PSMD2 in breast cancer cells can effectively inhibit cell proliferation and arrest cell cycle at G0/G1, which is caused by the up-regulation of p21 and p27." (PMID 38523673, 2024). "We then analyzed the endogenous interaction of these proteins in breast cancer cells using Co-IP assays with anti-PSMD2, RACK1, and β-catenin antibodies." (PMID 37848434, 2023). "In breast carcinoma cells, viability and clonogenicity were negatively affected upon PSMD2 repression, cells were arrested in G0/G1 phase, and the level of the proteins involved in the progression of the cell cycle (CDK6 and CCND1) was significantly decreased." (PMID 37529110, 2023). "Collectively, RACK1 competes with β-catenin for binding to the Armadillo-like helical domain of PSMD2 in breast cancer cells." (PMID 37848434, 2023). "Collectively, our findings suggest that RACK1 facilitates breast cancer progression by competitively inhibiting β-catenin binding to PSMD2, increasing β-catenin stability, and promoting WNT pathway activation." (PMID 37848434, 2023). "PSMD2 is also associated with the metastatic phenotype in the lung cancer cell line NCI-H460-LNM35 and lymph node metastasis in breast cancer." (PMID 35565454, 2022). "Emerging evidence shows PSMD2 is overexpressed in human cancers, including lung cancer, gastric cancer, breast cancer, which implies its vital roles in carcinogenesis." (PMID 36505799, 2022). "Overexpression of PSMD2 has been previously shown to be involved in the development of lung adenocarcinoma, breast cancer, and hepatocellular carcinoma." (PMID 34398824, 2021). "In breast cancer cells, RACK1 binds to PSMD2 within the proteasome and this binding prevents proteasome-mediated degradation of ubiquitinated β-catenin, resulting in the activation of the Wnt signaling pathway and promotion of breast cancer proliferation." (PMID 40940922, 2025). "PSMD2 knockdown inhibits breast cancer cell proliferation and arrests the cell cycle." (PMID 38745188, 2024). "In addition, we treated RACK1-silenced cells with MG132 and found that the binding ability of PSMD2 to poly-ubiquitinated β-catenin was significantly enhanced in both breast cancer cells." (PMID 37848434, 2023). "As expected, silencing of PSMD2 attenuated the degradation rate of β-catenin and increased its protein level, whereas overexpression of PSMD2 decreased the stability of β-catenin in breast cancer cells." (PMID 37848434, 2023). "We then silenced the expression of PSMD2 in breast cancer cells." (PMID 37848434, 2023). "Moreover, high expression of exogenous PSMD2 in breast cancer cells decreased the protein abundance of β-catenin and increased the rate of β-catenin degradation." (PMID 37848434, 2023). "Together, PSMD2 acts upstream of β-catenin and regulates its stability in breast cancer cells." (PMID 37848434, 2023). "Studies have reported that Psmd2 could regulate breast cancer cell proliferation and cell cycle progression by regulating p21 and p27 proteasome degradation." (PMID 35237384, 2022).
breast carcinoma (continued). "In addition, abnormal expression of PSMD2 (proteasome 26S subunit ubiquitin receptor, non-ATPase 2), a subunit of the 19S regulatory particle (RP) of the proteasome, has been reported in lung adenocarcinoma, breast cancer, and hepatocellular carcinoma." (PMID 34398824, 2021). "For example, PSMD1 could regulate breast cancer cell growth, and PSMD2 can regulate tumor cell proliferation in lung cancer and breast cancer." (PMID 31703613, 2019). "Expression of F-box only protein 22 (FBXO22) in HCC, UBR5 (ubiquitin protein ligase E3 component N-recognin 5) in colon cancer and PSMD2 (26S proteasome non-ATPase regulatory subunit 2) in breast cancer is upregulated; these genes regulate p21 stability by mediating ubiquitylation of p21." (PMID 31416295, 2019). "Previous study have showed that PSMD2 regulated the cell proliferation and the cell cycle progression in breast cancer via modulation of p21 and p27 proteasomal degradation, which suggest that this protein might be a potential therapeutic target." (PMID 31877708, 2019). "The levels of PSMD1, PSMD2, PSMD3, PSMD7, PSMD10, PSMD12, and PSMD14 are high in breast cancer tissue compared to normal tissues." (PMID 36934426, 2023). "The protein levels of MDC1, PSMB1, PSMB9, PSMD2, PSMD7, and PSMD14 were increased, while that of PARP3 was decreased in breast cancer tissues compared with normal tissues." (PMID 37350936, 2023). "Subsequently, we explored the protein levels of MDC1, PARP3, PSMB1, PSMB9, PSMD2, PSMD7, and PSMD14 in normal breast tissues and breast cancer tissues." (PMID 37350936, 2023). "PSMD2 and PSMD7 were shown to regulate breast cancer cell proliferation and cell cycle progression by regulating the proteasomal degradation of p21 and p27." (PMID 37349676, 2023). "Collectively, we identified PSMD2 as a novel binding partner of RACK1 and β-catenin in breast cancer cells." (PMID 37848434, 2023). "Consistent with the Immunohistochemistry (IHC) results, the expression of MDC1, PSMB1, PSMD2, PSMD7 and PSMD14 were significant augmented in breast cancer patients (P < 0.05)." (PMID 37350936, 2023). "We analyzed a prognostic model based on seven DDR genes, PSMD2, PSMD7, PSMD14, PARP3, MDC1, PSMB1, and PSMB9, reflecting an enhanced level of predicting the survival and prognosis of patients with breast cancer." (PMID 37350936, 2023). "PSMD2 is a member of the PSMD gene family, which promotes breast cancer cell proliferation through interacting with p21 and p27." (PMID 36292719, 2022). "PSMD2 is overexpressed in different types of tumors and cancer cell lines, and it is correlated with poor prognosis in HCC, breast cancer, lung and gastric adenocarcinomas." (PMID 35565454, 2022). "In this context, Deng and colleagues demonstrated that the expression of six proteasome subunits including PSMA1, PSMB5, PSMD1, PSMD2, PSMD8 and PSMD11 was increased over three-fold in breast cancer tissues when compared to adjacent normal tissues." (PMID 27966459, 2017). "Upregulated genes like INHBA, PSMD2 and OLR1 play a crucial role in breast cancer (BC) which may bring us some similarities between HNSCC and BC." (PMID 39749326, 2024). "In addition, we investigated the roles of MDC1, PSMB1, PSMD2, PSMD7, and PSMD14 in the invasion and metastasis of breast cancer." (PMID 37350936, 2023). "Furthermore, we investigated the function of the five highly expressed genes (MDC1, PSMB1, PSMD2, PSMD7, and PSMD14) in breast cancer MDA-MB-231 cells to test the prognostic model." (PMID 37350936, 2023). "The idea that PSMD1 and PSMD2 play important roles in the proliferation process of tumor cells, such as breast cancer cells and lung cancer cells, is not novel." (PMID 31703613, 2019). "We established a seven-gene prognostic model comprising MDC1, PARP3, PSMB1, PSMB9, PSMD2, PSMD7, and PSMD14 genes, which provides a basis for further exploration of a population-based prediction of prognosis and immunotherapy response in patients with breast cancer." (PMID 37350936, 2023).
breast carcinoma (continued). "PSMD2 physically interacts with p21 and p27 and mediates their degradation via the ubiquitin-proteasome pathway by cooperating with the deubiquitinating enzyme USP14, subsequently promoting cell proliferation and facilitating cell cycle progression in breast cancer." (PMID 37875476, 2023). "Thus, we reveal a novel mode of interaction between PSMD2, RACK1 and β-catenin, that may be a mechanism involved in regulating the activation of the WNT pathway, and targeting this pathway may be an effective way to treat breast cancer." (PMID 37848434, 2023). "Knockdown of PSMD2 did not affect the protein levels of β-catenin and RACK1 in two breast cancer cells." (PMID 37848434, 2023).
hepatocellular carcinoma (9 papers, 2019 to 2025). A malignant tumor that arises from hepatocytes. "Psmd2 regulates the expression of neo-lipid synthesis-related genes through p38-JNK and AKT signaling, thereby increasing the proliferation of HepG2 cells by promoting cellular lipid droplets, and highly expressed Psmd2 is significantly associated with poor prognosis in hepatocellular carcinoma." (PMID 35237384, 2022). "In hepatocellular carcinoma cells, PSMD2 knockout reduced the formation of lipid droplets and modulated the expression of genes associated with lipid synthesis through the p38-JNK and AKT signaling pathways." (PMID 37350936, 2023). "In hepatocellular carcinoma, PSMD2 can modulate cellular lipid metabolism to regulate HepG2 cell proliferation via p38-JNK and AKT signaling." (PMID 35754829, 2022). "To further validate the regulatory roles of PSMD1 and PSMD2 in lipid metabolism, we performed the same experiments using another human hepatocellular carcinoma cell line, Huh7." (PMID 31703613, 2019). "Therefore, the high expression levels of PSMD1 and PSMD2 probably enhanced hepatocellular carcinoma tumor cell proliferation." (PMID 31703613, 2019). "In the present study, we chose a hepatocellular carcinoma cell line, HepG2, to investigate the roles of PSMD1 and PSMD2 in cell proliferation and cellular lipid metabolism." (PMID 31703613, 2019). "However, the protein level of PSMD2 and PSMC3 didn’t change in other NEDD4L-KD turmor cells such as hepatocellular carcinoma (HCC) cells." (PMID 35236820, 2022).
lung adenocarcinoma (7 papers, 2013 to 2023). A carcinoma that arises from the lung and is characterized by the presence of malignant glandular epithelial cells. "Up to now, there is no studies have designed to investigate the association between PSMD2 expression and immune cell infiltration in lung adenocarcinoma." (PMID 35754829, 2022). "The genetic mutation of PSMD2 was also correlated with poor overall survival, disease-specific survival, and progression-free survival in lung adenocarcinoma." (PMID 35754829, 2022). "To identify the mutation characteristics of PSMD2 and its prognostic value in altered lung adenocarcinoma patients, we utilized an analysis on the cBioPortal database." (PMID 35754829, 2022). "Our results further indicated that the genetic mutation of PSMD2 was also correlated with poor overall survival, disease-specific survival, and progression-free survival in lung adenocarcinoma." (PMID 35754829, 2022). "Overall, these results suggest that genetic mutation of PSMD2 was correlated with poor prognosis in lung adenocarcinoma." (PMID 35754829, 2022). "PSMD2 had a high mutation frequency of 14% in lung adenocarcinoma." (PMID 35754829, 2022). "Furthermore, mutation characteristics of PSMD2 from the cBioPortal database also suggest that the altered group is associated with poor prognosis in overall survival, disease-specific survival, and progression-free survival in lung adenocarcinoma." (PMID 35754829, 2022). "Taken together, these results suggest that mRNA expression of PSMD2 is elevated in lung adenocarcinoma tissues." (PMID 35754829, 2022). "Based on our data, we conclude that PSMD2 is a potential biomarker for poor prognosis in lung adenocarcinoma." (PMID 35754829, 2022). "In this study, our results indicate that lung adenocarcinoma patients with high PSMD2 expression have poor overall survival and progression-free survival." (PMID 35754829, 2022). "To examine the clinical relevance of PSMD2 expression, we conducted the expression between different clinicopathological factors of lung adenocarcinoma patients with the Mann-Whitney U test." (PMID 35754829, 2022). "Protein expression from HPA also suggested that PSMD2 in lung adenocarcinoma tissue was higher than that in normal lung tissue." (PMID 35754829, 2022). "Univariate analysis showed that high expression of PSMD2 was significantly correlated with poor overall survival of lung adenocarcinoma patients (HR 1.694, 95%CI, 1.264–2.269, p < 0.001)." (PMID 35754829, 2022). "Our findings suggest that PSMD2 is a potential biomarker for poor prognosis and immune therapeutic target in lung adenocarcinoma." (PMID 35754829, 2022). "Our findings link the upregulation of PSMD2 with the poor prognosis and propose a therapeutic immunological target for lung adenocarcinoma." (PMID 35754829, 2022). "To explore the total protein expression of PSMD2 between lung adenocarcinoma and normal tissues, we analyzed CPTAC with the UALCAN dataset." (PMID 35754829, 2022). "Our data indicate that PSMD2 is an independent factor for overall survival in lung adenocarcinoma patients." (PMID 35754829, 2022). "In this study, we first examined the expression of PSMD2 in lung adenocarcinoma in the TCGA and UALCAN databases." (PMID 35754829, 2022). "In this study, we reported that the expression level of PSMD2 is significantly elevated in lung adenocarcinoma and its upregulation is a reliable predictor of high T stage, lymph node metastases, and high TNM stage." (PMID 35754829, 2022). "Given our results, it is likely that PSMD2 is involved in tumorigenesis and metastasis of lung adenocarcinoma." (PMID 35754829, 2022). "Our findings on the prognostic value of PSMD2 in lung adenocarcinoma are consistent with these reports." (PMID 35754829, 2022). "In conclusion, our findings showed that PSMD2 expression is significantly elevated in lung adenocarcinoma and its upregulation is a reliable predictor of high T stage, lymph node metastases, and high TNM stage." (PMID 35754829, 2022).